HCK (HCK proto-oncogene, Src family tyrosine kinase)
Diseases named in the same sentence as HCK in open-access papers (continued):
Sharing a sentence is not in itself a finding about the gene and the disease.
cancer (29 papers, 2011 to 2025). A tumor composed of atypical neoplastic, often pleomorphic cells that invade other tissues. "A growing body of research shows that HCK plays a role in a variety of diseases, such as inflammation, fibrosis, and cancer." (PMID 39247797, 2024). "Actually, HCK overexpression has also been observed in NSCLC and HCK activation has been reported to force the recruitment of immune cells into tumors in many cancers, which was consistent with the phenotype of up-regulated MRPL15 in our present study." (PMID 34026630, 2021). "Of all of the other family members (FYN, YES, BLK, YRK, FGR, HCK, LCK, and LYN) cSrc is the most often associated with cancer progression." (PMID 33841333, 2021). "Results of the CCLE analysis showed the level of HCK mRNA transcripts in AML ranks 1th among many cancer cell lines." (PMID 34167558, 2021). "Activated membrane SFKs member, FGR and HCK can work in parallel to promote cancer development and weaken lymphocytic infiltration." (PMID 33162805, 2020). "Overall, this research found that HCK expression was higher in cancer tissues than that in non-cancer tissues and was related to distant metastasis and death." (PMID 33162805, 2020). "UALCAN analysis also showed that the level of HCK promoter methylation was higher in cancer tissues than in non-cancer tissues." (PMID 33162805, 2020). "Differential HCK expression was found in 20 human cancers based on the database, including solid tumors." (PMID 33162805, 2020). "Consistent to above results, the level of HCK mRNA expression was significantly higher than in non-cancer tissues (P<0.01)." (PMID 33162805, 2020). "Further, we extracted several neighboring genes that were related to HCK from Coexpedia to determine the potential molecular regulation mechanisms of HCK in cancer and other diseases." (PMID 33162805, 2020). "In Class I we identified mammalian onco-homologs assuming oncogenic functions with onco-signatures always intact in cancer, such as HCK and LYN." (PMID 29844492, 2018). "It was shown that MAP3K14, PTN, ACVR1 and HCK sharing different DNA methylation and gene expression across cancers were relatively high degree distribution in PPI network." (PMID 25774687, 2015). "HCK is a member of the Src family of protein tyrosine kinases that have been shown to play a role in a variety of diseases, including inflammation, fibrosis, and cancer." (PMID 39247797, 2024). "FLT3 and HCK are described as attractive targets for cancer therapy." (PMID 38491064, 2024). "However, HCK has opposite effects in non-cancer cells by promoting macrophage inflammatory activation." (PMID 37463911, 2023). "HCK plays a pivotal role in innate immunity and was overexpressed in various cancers." (PMID 37035749, 2023). "Several studies have shown that HCK plays a major role in cancer development or may be an anticancer target." (PMID 34363435, 2021). "Haematopoietic cell kinase (HCK), a vital member of the Src family of kinase proteins, plays crucial roles in cancer progression and may act as an anticancer target; however, the mechanism by which HCK enhances OS development remains unexplored." (PMID 34363435, 2021). "The overexpression of HCK may be involved in tumorigenesis, cancer progression, and survival outcomes." (PMID 33162805, 2020). "Also, FCGR1A is involved in many pathophysiological processes and is closely related to FCGR3A, SYK, and HCK in various cancers." (PMID 33344503, 2020). "Furthermore, inhibition of HCK expression can reduce the cancer burden in the mice model." (PMID 33162805, 2020). "These genes were presumably involved in cancer (SMG6, HCK), cellular growth (CPVL), reproduction (ADGB, CRISP1, CTTNBP2NL, WDR78), and nervous system (AUTS2, CNTNAP2, CPVL, SRGAP2)." (PMID 40149444, 2025). "Specifically, Oncomine analysis, GEPIA analysis and UALCAN analysis showed that a higher level of HCK mRNA transcripts in cancer tissues than in non-cancer tissues." (PMID 33162805, 2020).
cancer (continued). "The level of HCK mRNA transcripts was also significantly higher in cancer tissues than that in non-cancer tissues in our specimens (P<0.01)." (PMID 33162805, 2020). "In line with this, knock-down of HCK by siRNA substantially reduced expression of the anti-apoptotic protein MCL-1, which coincided with increased expression of pro-apoptotic BAX and enhanced death of cancer cells." (PMID 26087188, 2015). "Hematopoietic cell kinase (HCK) is a member of the SRC family of cytoplasmic tyrosine kinases (SFKs) that are expressed in cells of the myeloid and B-lymphocyte lineages and may serve as therapeutic targets in immune cells and cancer cells." (PMID 36536067, 2022). "The ratio of HCK expression was higher in cancer tissues than in non-cancer tissues." (PMID 33162805, 2020). "However, we found that the level of HCK mRNA expression was significantly higher in cancer tissues than that in non-cancer normal tissues (P<0.01)." (PMID 33162805, 2020). "Finally, these results of Oncomine analysis, GEPIA analysis and UALCAN analysis showing higher HCK expression in cancer tissues than that in non-cancer tissues were confirmed in fresh cancer tissues." (PMID 33162805, 2020). "Given the high frequency of excessive HCK activation in these cancers and its correlation with a poor prognosis on one hand, and the relatively mild phenotype displayed by HCKKO mice on the other hand, HCK may be a promising target for cancer treatment." (PMID 26087188, 2015).
infection (6 papers, 2016 to 2025). The state of being infected such as from the introduction of a foreign agent such as serum, vaccine, antigenic substance or organism. "Most pathways associated with HCK were linked to immune function and infection (Figure 2Elower), with 4 out of 8 HCK‐associated immune pathways upregulated." (PMID 39666559, 2025). "We found that SIAT-NExt cells, and to a lesser extent hCK-NExt cells, exhibit increased HA binding to the cell surface and improved susceptibility to infection by recent H3N2 virus strains compared to MDCK cells." (PMID 37794004, 2023). "Thus, engineering MDCK cells to overexpress ST6GAL1 in SIAT and hCK substantially improved infection and propagation of recent H3N2 viruses." (PMID 37794004, 2023). "On the other hand, apoptotic inducers such as hematopoietic cell kinase (HCK), BIK, and BNIP3L are downregulated during early infection." (PMID 27303657, 2016).
kidney (1 paper, 2023). "Based on these data we investigated the role of HCK in regulating macrophage function during kidney injury." (PMID 37463911, 2023).
kidney disease (1 paper, 2023). "In addition, we developed a more selective boron containing HCK inhibitor and we show that this inhibitor has anti-fibrosis and anti-inflammatory effects in cells and animal models of kidney disease." (PMID 37463911, 2023). "We demonstrated that HCK is the main SFK in macrophages and highly regulated in kidney disease, but we could not rule out the role of other SFK members in kidney disease." (PMID 37463911, 2023). "We described here BT424, a relatively selective inhibitor of HCK and BT424 does not affect podocyte injury and therefore, we believe that BT424 is a better drug to target HCK as an anti-inflammatory and anti-fibrosis therapy in patients with kidney disease." (PMID 37463911, 2023).
HCK also shares sentences with these, for which no sentence is quoted: mantle cell lymphoma (3 papers); chronic lymphocytic leukemia (2); hematological malignancies (2); non-small cell lung carcinoma (2); renal carcinoma (2); Alzheimer disease (1); autoimmune disease (1); benign breast disease (1); brain tumors (1); cerebrovascular diseases (1); chordoma (1); Cognitive impairment (1); colorectal tumors (1); coronary artery disease (1); cutaneous vasculitis (1); ductal breast carcinoma (1); ear infection (1); endothelial dysfunction (1); hearing loss (1); heart failure (1); hemorrhage (1); Hypertension (1); hypovitaminosis D (1); inflammation (1); interstitial lung disease (1); invasive ductal breast carcinoma (1); ischemic cardiomyopathy (1); liver fibrosis (1); malignant brain tumors (1); meningioma (1).
A further 15 diseases each share a sentence with HCK in 1 paper.